FAP (fibroblast activation protein alpha)
Diseases named in the same sentence as FAP in open-access papers (continued):
Sharing a sentence is not in itself a finding about the gene and the disease.
cancer (continued). "Other studies have investigated the potential of using FAP as a target for cancer treatments with different strategies including cancer vaccines, FAP-specific CAR-T cell treatment, and bispecific antibody-guided immunotherapy." (PMID 38540158, 2024). "We also found that high enrichment of αSMA + FAP + mr-CAFs predicted poor prognosis through pan-cancer analysis using TCGA datasets." (PMID 39334513, 2024). "This review examines the biological underpinnings of FAP in the TME, the design of FAPI-based imaging agents, and their evolving role in cancer diagnostics, highlighting the potential of FAP as a target for precision oncology." (PMID 39765634, 2024). "Generally, αSMA + FAP + mr-CAFs express high collagen levels and function as a barrier to effective drug delivery to cancer cells." (PMID 39334513, 2024). "The results highlight the broad utility of FAP-targeted imaging for augmenting early diagnosis by facilitating the detection of multiple cancers." (PMID 39518426, 2024). "The other major trend is the progress on imaging modalities that target FAP, which has been demonstrated as an excellent marker for several cancer indications." (PMID 39518426, 2024). "- EnAd-FAP-BiTE mediated T cell activation, their subsequent proliferation, and the induction of cytotoxicity in cancer cells.- EnAd-FAP-BiTE induces repolarization of resident TAMs in ascites samples.- EnAd-FAP-BiTE increased infiltration of T cells." (PMID 38464532, 2024). "Simlukafusp alfa with FAP targeting and atezolizumab (atezo) represent two distinct approaches in cancer therapy, each with unique mechanisms of action and therapeutic targets." (PMID 38558814, 2024). "Several “CAF markers”—including alpha-smooth muscle actin (αSMA), vimentin, and fibroblast activation protein alpha (FAP)—have been proposed, but their expression varies between different cancer types and CAF subpopulations." (PMID 39567960, 2024). "Pan-cancer expression analysis of FAP on 31 different types of cancer identified the increased expression of FAP in tumors compared to normal tissues." (PMID 39579201, 2024). "As a result, FAPI is increasingly being used to diagnose and target cancers with high FAP expression." (PMID 38505595, 2024). "PDXs were screened for FAP expression because of their superiority in recapitulating the spatial structure and heterogeneity of patients’ cancer." (PMID 39266288, 2024). "Being specifically expressed in pathological conditions including multiple types of fibrosis and cancers, FAP is an optimal target for diagnostics and treatment." (PMID 38540158, 2024). "Conversely, FAP expression was significantly increased in all cancer stages compared to controls (p < 0.0001)." (PMID 38606999, 2024). "CAR‐T cell responses to FAP stimulation in vitro were initially measured by co‐culturing CAR‐T cells with FAP‐expressing long‐term cancer cell lines." (PMID 38975278, 2024). "The transmembrane prolyl protease fibroblast activation protein (FAP) is expressed on the surface of highly protumorigenic CAFs found in the stroma of nearly every cancer of epithelial origin." (PMID 38747612, 2024). "α-SMA and FAP were observed to be expressed by one subset of cancer cells and integrin α11 and collagen-1 by another in IMC." (PMID 38803925, 2024). "This work identifies FAP as a highly promising TME protein for antibody-based therapies targeting CRC secondary to its expression across a wide range of these cancers and limited expression in the liver and colon." (PMID 39335130, 2024). "Fibroblast activation protein (FAP) is specifically expressed on proliferating fibroblasts, and its presence on the surface of CAFs can be detected in many types of cancer with poor prognoses." (PMID 39421736, 2024). "The overall-survival analysis of the FAP gene was then compared across multiple cancer types to estimate the HR and median survival at a significant p-value." (PMID 39579201, 2024).
cancer (continued). "We found that FAP is not only high in primary cancers and low in normal colon tissue but also highly expressed within metastases to the liver but not adjacent normal liver tissue." (PMID 39335130, 2024). "The FAP+CAFs were discovered to utilize the CXCR4/CXCL-12 axis to effectively exclude CD8+ T cells from the region containing cancer cells by releasing CXCL-12, ultimately preventing the CD8+ T cells from reaching the TME." (PMID 39609700, 2024). "Nevertheless, the potential inaccuracy introduced by this approach is relatively minor‐less than 30% of GBMs contain FAP+ cancer cells, which in most cases constitute less than 10% of the cells." (PMID 38705944, 2024). "FAP-targeted PET/CT using 68Ga or 18F-labeled FAP inhibitors (FAPIs) is a highly promising imaging tool for the diagnosis, staging, monitoring recurrence, and metastasis of various cancers." (PMID 39376651, 2024). "Cancer cell lines transduced to (over-)express human FAP are the most commonly used models to evaluate the potential of novel FAP-targeted radiopharmaceuticals in preclinical studies." (PMID 39718718, 2024). "The specificity of FAP to pathological conditions makes it an optimal target for diagnostics and the treatment of diseases such as cancer, and its potential is being investigated through multiple approaches." (PMID 38540158, 2024). "With FAP-TRT the cancer cells are generally targeted indirectly via the FAP-expressing CAFs, in contrast to currently approved TRT strategies (e.g., targeting somatostatin receptor subtype 2)." (PMID 39718718, 2024). "Due to the preferential expression of FAP in CAFs and their scarcity in normal tissues, radiolabeled FAP inhibitors (FAPIs) have emerged as valuable tools for cancer theranostics, particularly in tumors characterized by extensive fibrotic stroma." (PMID 39770505, 2024). "This revealed that αSMA + FAP + mr-CAFs correlated with poor prognosis in multiple cancer types, including BLCA (P = 0.03), KIRC (P = 0), PAAD (P = 0.002), LUAD (P = 0.022), LUSC (P = 0.045) and a poor tendency in ESCA (P = 0.123)." (PMID 39334513, 2024). "The FAP gene expression across various cancers and its functional and survival outcomes were estimated using computational approaches." (PMID 39579201, 2024). "Genes implicated in extracellular matrix interactions and tissue remodeling, such as SPARC and FAP, frequently contribute to tissue development, repair, and the cancer microenvironment." (PMID 39336798, 2024). "The field of oncology is increasingly dedicated to the advancement of FAPI, including assessment of the specific indications for FAPI PET imaging, development of novel FAPI-based radiotracers, and FAP-targeted radioligand therapy in refractory cancers." (PMID 39758423, 2024). "To further understand the transcriptional programs behind αSMA + FAP + mr-CAFs and their relationship to the prognosis of cancer patients, we identified gene signatures with distinct expression patterns across αSMA + FAP + mr-CAFs by Hotspot analysis." (PMID 39334513, 2024). "Given the potential role of FAP in the pathogenesis of fibrosis and cancer, several therapeutic strategies seek to target this protein, from selective inhibitors to anti-FAP chimeric antigen receptor (CAR)-T cells or even recent theragnostic ligands." (PMID 39188902, 2024). "The remaining articles focused on the expression of FAP in cancer stroma and FAP-targeted immunotherapy." (PMID 39758423, 2024). "FAP is overexpressed on activated fibroblasts and coincides with poor prognosis in cancers, which has made FAP-targeted imaging and therapy appealing." (PMID 38459511, 2024). "It has been reported that FAPα expression in cancer stroma is a factor in the poor prognosis of patients with cancer." (PMID 39596363, 2024). "FAP expression is typically low or undetectable in normal tissues, but is overexpressed in 90% of cancers." (PMID 39239526, 2024).
cancer (continued). "While the FAP+ myCAF clusters—namely ECM-myCAF, TGFβ-myCAF and IFNαβ-myCAF—are observed in close proximity to cancer cells, the FAP+ Detox-iCAF cluster is detected around blood vessels." (PMID 38561380, 2024). "As a result, FAP is overexpressed in the neoplastic microenvironment of more than ninety percent of epithelial tumors and is a major contributor to cancer progression." (PMID 38334567, 2024). "Detection of Cancer-Associated Fibroblasts (CAF) markers showed positivity for SMA and FAP, and Sanger sequencing detected mutations in IDH2 (R172G) and PIK3CA (H1047R) genes." (PMID 39624628, 2024). "These stromal cells, particularly through their expression of fibroblast activation protein (FAP), are involved in cancer progression by modifying the extracellular matrix, promoting angiogenesis, and suppressing immune responses." (PMID 39765634, 2024). "In contrast, FAP expression is minimal in normal tissues, making it an ideal target for cancer diagnosis and therapy." (PMID 39770505, 2024). "FAP expression was found on the surface of fibroblasts in the stroma of 90% of different cancers including breast, colorectal, bladder, lung and ovarian." (PMID 39338305, 2024). "The testing of these inhibitors as pharmacologic agents (and FAP-directed antibodies) for the treatment of cancer has had limited clinical success to date." (PMID 39065684, 2024). "Recently, PET imaging targeting fibroblast activation protein (FAP) has shown great potential in depicting non–18F-FDG-avid malignant tumors." (PMID 38272706, 2024). "IL-10’s role in cancer is complex, evidenced by its contribution to both immune suppression and stimulation within the FAP+ stromal compartments of diverse tumors such as NSCLC, PDAC, CRC, and RCC." (PMID 39035007, 2024). "Early efforts of targeting FAP for cancer treatment started with radioimmunotherapy using radiolabeled antibodies (e.g., 131I-mAbF19)." (PMID 39766079, 2024). "Of patients whose primary cancers stained positively for FAP expression (n = 70), 97.1% also expressed FAP in their metastasis." (PMID 39335130, 2024). "Recently, FAPI-PET, which targets FAP within the microenvironment surrounding cancer cells, has garnered significant attention." (PMID 39519118, 2024). "For example, ablation or inactivation of CAFs using general myofibroblast markers, such as αSMA, FAP, and type-I collagen, induced severe toxicity and promoted cancer aggressiveness in mouse models." (PMID 38360876, 2024). "CAF-targeted imaging probes, particularly those directed at FAP, have shown remarkable potential in advancing cancer diagnosis and therapy." (PMID 39770505, 2024). "In contrast, in lung (NSCLC) and head and neck (HNSCC) cancers, high FAP+CAF correlated with more endothelial cells and pericytes, important for blood vessel stability." (PMID 39035007, 2024). "In conclusion, our data supported the efficacy of immunotherapy combined with 177Lu-LNC1004 for cancer patients with FAP-positive tumors." (PMID 38825657, 2024). "This interaction and processing are likely different for FAP expressed by CAFs, compared to targets expressed by genetically unstable cancer cells." (PMID 39718718, 2024). "The role of cancer-associated fibroblasts (CAFs) in the immune microenvironment was acknowledged by selecting marker genes ACTA2, FAP, PDGFRB, and NOTCH321–23, aiding in dimensionality reduction for the clustering analysis, which identified five CAF clusters." (PMID 38740918, 2024). "Detection of differential markers subtyped the cells of mesenchymal origin (vimentin, desmin, cadherin-11, podoplanin, CD74, S100A4, CD44, FAP), which vary according to the functional differentiation and specialization in sites of cancer tissue." (PMID 39575252, 2024). "We scored multiple cancer types from The Cancer Genome Atlas (TCGA) with these signatures based on their expression of αSMA + FAP + mr-CAF genes." (PMID 39334513, 2024).
cancer (continued). "The role of FAP in cancer is controversial, with studies demonstrating both positive and negative prognostic correlations." (PMID 39618102, 2024). "In humans, FAP is also upregulated in other fibrotic diseases as well as non-fibrotic diseases, and, importantly, in various types of cancers." (PMID 39188902, 2024). "FAP imagining is a new approach in pan-cancer theranostics based on highly potent targeting vectors." (PMID 38999044, 2024). "Simlukafusp alfa is intended to be given in combination with cancer immunotherapies that act via immune effector cells because FAP-IL2v increases the population of activated immune effector cells." (PMID 39140264, 2024). "To gain a deeper understanding of how FAP+ CAFs contribute to cancer progression, we conducted a ST RNA-seq analysis to map the spatial patterns of FAP+ CAFs." (PMID 39239526, 2024). "Small molecules and monoclonal antibodies capable of targeting and inhibiting FAPα were developed for cancer treatment." (PMID 39273006, 2024). "Currently, FAP-transduced cancer cell lines are the most commonly used model for both in vitro and in vivo evaluation of FAP-targeted radiotracers, in particular the human fibrosarcoma cell line HT1080 and the human embryonic kidney cell line HEK293." (PMID 39718718, 2024). "Since 1990, researchers have proposed using FAP antibodies as radioisotope-labeled ligands or as therapeutic agents in combination with toxic chemotherapeutic substances for cancer therapy." (PMID 39758423, 2024). "The cancer-specific expression of FAP encourages the use of FAP as a potent target for cancer therapy." (PMID 39579201, 2024). "Our results emphasize FAP’s multifaceted role in therapy response, suggesting its potential as a cancer immunotherapy biomarker." (PMID 38558814, 2024). "This evolution began with the discovery of the F19 monoclonal antibody recognizing FAP in various epithelial carcinomas, leading to immunotherapy and immune-combination chemotherapy." (PMID 39758423, 2024). "Subsequently, FAP was also identified in the reactive stroma of epithelial carcinomas, granulation tissue during wound healing, and malignant cells of bone tissue." (PMID 39758423, 2024). "Above experiments verified the potential of FAP-targeted CARTs in lysing human FAP positive carcinoma and CAFs in vivo." (PMID 39086477, 2024). "Because of this, FAP has been identified as a promising immunotherapy target for carcinomas which are typically heavily infiltrated with fibroblasts, such as those of prostate, breast, lung and pancreas." (PMID 38975278, 2024). "The FAP expression level within carcinoma is in line with previous studies, which showed that FAP is expressed in more than 90% of cases." (PMID 38397199, 2024). "FAP-expressing CAFs have been found in over 90% of epithelial carcinomas, and high FAP expression is associated with poor prognosis and worse treatment outcomes in multiple cancers." (PMID 39073475, 2024). "In general, FAP expression is indeed low in normal adult tissues, but becomes upregulated in almost all carcinomas." (PMID 38158643, 2024). "FAP is one of the most strongly expressed genes in the stroma of solid tumors and is upregulated in over 90% of epithelial carcinomas." (PMID 39030445, 2024). "The FAP-specific antibody sibrotuzumab was considered clinically safe and effective in phase I trials in advanced cancer." (PMID 37963845, 2023). "Fibroblast activation protein (FAP) is highly expressed in more than 90% of epithelial tumors, which makes FAP a promising target for diagnosis and therapy of various types of cancers." (PMID 37277339, 2023). "Although there are some studies examining the use of FAP-targeted radioligands for in-vivo imaging and targeted nucleotide therapy for a variety of cancers, including CRC, this field of research has yet to be fully developed." (PMID 37614665, 2023). "FAP expressed by CAFs is highly upregulated in various cancers and is typically used as a prognostic marker." (PMID 36598731, 2023).
cancer (continued). "FAP is a significant surface marker of CAFs and closely relevant to occurrence and development of cancers." (PMID 37752545, 2023). "When considering FAP as a promising tool in new cancer diagnostics and therapeutics, one should also take into account the immunohistochemical scoring system that is used to quantify the FAP expression." (PMID 37614665, 2023). "FAP-targeted imaging has so far shown to have impressive results and up-and-coming potential in a wide range of cancers." (PMID 37608378, 2023). "Similar findings were also observed in mouse model of COAD and STAD, results showed that co-injection of cancer cells and FAP positive cells led to anti-PD-1 treatment resistance in mice." (PMID 37325617, 2023). "Targeted depletion of fibroblasts has been achieved in the context of cancer by targeting FAP-expressing cells, but this led to adverse effects due to FAP expression in healthy tissues, especially bone marrow." (PMID 36745597, 2023). "One molecule of particular interest on the CAF is fibroblast activation protein (FAP), which has been discovered to be widely expressed in the pan-cancer stroma." (PMID 35951090, 2023). "Another German group in 2022 administered 177Lu-FAP-2286 to cancer patients after a positive 68Ga-FAPI scan." (PMID 36835275, 2023). "Blocking the PI3K/AKT/mTOR signaling pathway with the dual PI3K/mTOR inhibitor BEZ235 repressesed cancer-promoting effect of FAP." (PMID 37752545, 2023). "FAP is a membrane-bound protease under investigation as a pan-cancer target, given its high levels in tumors but limited expression in normal tissues." (PMID 37086273, 2023). "FAP is overexpressed in malignant tissue on activated fibroblasts on a variety of malignant tumors such as breast, colorectal, pancreatic, melanoma, myeloma, gastric, brain, and ovarian carcinomas while it shows less abundance in normal healthy tissue." (PMID 37284857, 2023). "FAP expression becomes highly upregulated in multiple types of cancer, and it is predominantly observed in CAFs." (PMID 37099374, 2023). "The use of FAP-specific inhibitors as [68Ga] Ga-FAPI which is a tumor-targeting radiopharmaceutical has opened up a new area of cancer research." (PMID 37568769, 2023). "Preliminary evidence has generated raging scientific interest in FAP as the next billion-dollar pan-cancer target in the field of nuclear medicine." (PMID 37370912, 2023). "FBP binds to a protein called fibroblast activation protein (FAP), which is expressed on both TAMs and cancer cells." (PMID 37601380, 2023). "In this work, we found (2S,4S)-4-fluoropyrrolidine-2-carbonitrile scaffold to be a promising pharmacophore for the design of FAP-targeted radioligands for cancer diagnosis." (PMID 37110717, 2023). "Fibroblast activation protein-alpha(FAPα) is a major regulator of the microenvironment in a varietyof diseases and is emerging as a cancer biomarker for cancer diagnosisand therapy." (PMID 39473938, 2023). "Here, we comprehensively map the FAP expression profile, prognostic outcome, genetic alteration, immune infiltration across over 30 types of human cancers through multiple datasets including TCGA, CPTAC, and cBioPortal." (PMID 37166418, 2023). "Given the extensive expression of FAP in diverse cancers, we further investigated the correlation between FAP expression and clinical prognosis." (PMID 37166418, 2023). "FAP overexpression has been targeted in experimental cancer imaging and therapeutics using antibodies, peptides, enzymatic inhibitors, vaccines, immuno-conjugates, and chimeric antigen receptor T cells." (PMID 37370912, 2023). "Recently, FAP has attracted extensive attention for its potential as a cancer imaging and therapeutic target." (PMID 36864362, 2023). "We found a strong pSTAT3 staining in our mIHC analysis, which was detected in both cancer cells (E-cadherin+) and stromal cells (PDGFRβ+), including CAFs (FAP+)." (PMID 37400436, 2023).